CCL2 (C-C motif chemokine ligand 2)
Diseases named in the same sentence as CCL2 in open-access papers (continued):
Sharing a sentence is not in itself a finding about the gene and the disease.
tumor (continued). "Tumor cells secrete chemokines (CCL2, CCL7, and CXCL12) and cytokines (VEGF) to recruit peripheral blood monocytes into tumor tissues and induce them to differentiate into TAMs." (PMID 37064113, 2023). "MMPs together with VEGF-C, activates the CCL2/CCR2 signaling pathway and attracts circulating monocytes into the TME, thereby promoting tumor growth, expansion, and metastasis." (PMID 38033495, 2023). "The results of RT-qPCR showed that the expression levels of CCL2, CCL22, TNF-α and IFN-γ in tumor tissues were significantly increased after TCS treatment." (PMID 36674931, 2023). "Overexpression of FAP can activate the FAP-STAT3 pathway that drives the expression of CCL2, upregulating the recruitment of MDSCs into the TME, further promoting tumour development." (PMID 39935547, 2023). "The tumor’s inflammatory milieu and secretion of cytokines, such as CSF-1 and CCL2 (also known as monocyte chemoattractant protein-1), contribute to the attraction and polarization of TAMs into distinct subtypes." (PMID 37895012, 2023). "Malignant cells can secrete M2-like cytokines such as IL-10, CCL2, CXC12, VEGF, and PDGF to recruit more monocytes and M0 macrophages to the tumor sites." (PMID 37108657, 2023). "In experimental BC models (tumor cells from MMTV-PyMT mice and MCF-7 cells), estradiol enhanced macrophage influx and angiogenesis through increased release of CCL2, CCL5, and VEGF." (PMID 37208442, 2023). "In this regard, the CCL2/CCR2 axis attracts a lot of attention; it is known that its blocking is an effective approach to inhibit macrophage recruitment in tumor sites." (PMID 37999184, 2023). "Increases in pro-inflammatory (TNFα, IL-6, and MHC-II) and decreases in pro-tumor (VEGF, CCL2, and CD206) markers in WT tumor-educated BMDMs treated with 100 nM CDDO-Me suggest beneficial polarization of macrophages in vitro." (PMID 36670978, 2023). "Since tumor-derived CCL2 also recruits MSCs to the TME, an established CCL2 paracrine among tumor cells, MSCs, and TAMs in TME can support malignant progression." (PMID 36672395, 2023). "CAAs increase the levels of CCL2 to recruit TAMs, which release the IL-15/IL-15 receptor complex to reduce C-X3-C motif chemokine ligand 1 (CX3CL1) expression in tumor cells." (PMID 36765683, 2023). "It is noteworthy that cytokines such as CCL2, CCL5, and CSF1 were found to be involved in the attraction of MDSCs to the tumor site." (PMID 37033447, 2023). "Expression of chemokine receptors that match ligands secreted by the tumor such as CCL2, CCL22, CXCL16, CX3CL1, CXCL1 and CXCL8 can enable CD8+ T cells to enter the tumor." (PMID 37301772, 2023). "Another study used mNOX-E36, a chemokine C-C motif ligand 2 (CCL2) inhibitor, to block TAM recruitment and angiogenesis in CLL2-expressing rat GBM models, which ultimately decreased tumour volume." (PMID 37686652, 2023). "Application of CCL2 antagonists resulted in decreased MDSC infiltration and inhibited tumor development." (PMID 38313431, 2023). "MSC-secreted factors known to activate tumor cell growth and proliferation of other cancer entities are, for example, CCL2/MCP-1, angiogenin, and VEGF." (PMID 37781195, 2023). "In order to study the role of CCL2 in a network consisting of tumor cells, MSCs, and TAMs in the TME, we disrupted the CCL2 gene in the transgenic adenocarcinoma of the mouse prostate (TRAMP)-C2 cell line." (PMID 36672395, 2023). "In the treated group, the LIVP-RFP cytokine analysis suggested elevation of CXCL10 in the tumor samples and IFN-α, IFN-γ, CCL2, CCL3, CXCL9, and CXCL10 in the sera samples." (PMID 37112810, 2023). "In this study, we found that FAM171B-induced CCL2 modulated the TME by promoting the infiltration and M2 polarization of TAMs, ultimately leading to tumor progression." (PMID 37915048, 2023).
tumor (continued). "Macrophages are recruited and educated by multiple factors in the TME, including colony-stimulating factor-1 (CSF1), GM-CSF, TGF-β, IL-1, IL-4, CCL2, CCL5, immune complexes, complement, histamine, tumor-derived non-coding RNAs." (PMID 38008741, 2023). "Neutrophil cluster 6 also has high expression of Ccl2, Ccl3, Ccl4, Ccl5, and Cxcl2, which are inflammatory mediators involved in MDSC migration to and activation in the tumor microenvironment." (PMID 37483625, 2023). "The activated TAMs in the residual tumor in turn produced more TNF-α and CCL2, resulting in enhanced inflammation." (PMID 36831664, 2023). "Targeting both CCL2/CCR2 and CSF-1/CSF-1R axis is therefore relevant to a tumor that overexpresses M-CSF, CCL2 and other chemokines that bind to CCR2 such as CCL7." (PMID 38076998, 2023). "In this study, a subset of iCAFs that expresses high levels of the chemokine CCL2, known as ICAM1+ iCAFs, was identified and was found to recruit MDSCs (THBS1+ monocytes) to hypoxic tumor areas by binding to the receptor CCR2." (PMID 37743226, 2023). "The CCL2 inhibitor, mNOX-E36, was shown to decrease TAM recruitment, angiogenesis, and tumor volume in a rat model of GBM." (PMID 37275361, 2023). "FAP+ fibroblasts have also been identified in PDAC as tumor-promoting CAFs, performing possibly through stromal-derived factor 1 (SDF-1) and C-C motif chemokine ligand 2 (CCL2) dependent manner." (PMID 36793444, 2023). "Blocking the SCF-1α-CCL2 axis inhibits the recruitment of CCR2+ macrophages into tumor tissues and further suppresses the metastasis of tumor cells." (PMID 36593475, 2023). "A linear regression analysis revealed that tumor levels of TNC and CCL2 each correlated with myeloid cell markers, including F4/80 (ADGRE1), CSFR1,and CX3CR1, but not with CCR2, with a higher correlation of TNC than CCL2 at the 3 week time point." (PMID 37176074, 2023). "The authors speculated that a therapeutic strategy aiming at enhancing the pre-existing anti-CCL2 antibodies might be beneficial as the sera concentration of these antibodies might not be elevated enough to completely suppress monocyte infiltration and tumor cell migration." (PMID 37251376, 2023). "Mast cells are recruited to the TME by cytokines produced by tumor cells such as vascular endothelial growth factors (VEGFs), angiogenic hormone (ANGPT1), CCL2, and CXCL12 chemokines." (PMID 37161430, 2023). "Th17 cells can stimulate CD8 + CTL response through IL-2 and pMHC I, and stimulate the expression of CCL2 and CCL20 in tumor microenvironment to promote the recruitment of various inflammatory leukocytes (DCs, CD4 + and CD8+ T cells)." (PMID 36874093, 2023). "In particular, mural cell-derived CCL2 stimulated tumor cell MEK1-ERK1/2-ROCK2-dependent signaling and enhanced tumor cell survival and tumor growth." (PMID 37208442, 2023). "CCL2 binds to the homologous receptor CCR2, a signaling pair that has been shown to have a variety of protumorigenic effects, from mediating tumor growth and angiogenesis to recruiting and usurping host stromal cells to support tumor progression." (PMID 37880682, 2023). "These subpopulations of TAMs in the TME suggest support for tumor progression through various mechanisms, including suppression of immune cells by potent chemokines (e.g., MRP8-14, CCL2)." (PMID 37958292, 2023). "Recent studies have provided compelling evidence that targeted inhibition of CCL2/CCR2 with specific drugs can effectively suppressed the recruitment of TAMs and impede tumor progression and metastasis in lung, liver, and breast cancer models." (PMID 37654704, 2023). "For example, an anti-CCL2 antibody, carlumab (CNTO888), can inhibitor macrophage infiltration to the tumor in mice, which has been applied in clinical trials to treat solid tumors and metastatic castrate-resistant prostate cancer." (PMID 36816959, 2023).
tumor (continued). "TAMs in HCC can secrete various cytokines and chemokines, such as IL-1β, IL-6, TNF, CCL2, and CXCL10, promoting tumour cell proliferation and NF-κB-mediated protection against cancer cell apoptosis, which is associated with a poor prognosis in HCC patients." (PMID 37542324, 2023). "To interrogate the role of CCL2 in anti-tumor NK cell responses in PDAC, we first engineered KPC PDAC cell lines to express a Ccl2 cDNA (or an Empty vector as a control)." (PMID 37142692, 2023). "Relatedly, it was demonstrated that CCL2, CCL11, CCL16, and CCL18 support tumor angiogenesis as well as endothelial cell survival." (PMID 36980182, 2023). "Prior to conducting the assay, we identified a subset panel of factors known to mediate the induction of apoptosis in tumor cells: IL-27, IL-1b, IL-2, CXCL10, IL-12p70, G-CSF, IFN-g, TNF-a, IFN-a, CCL2, IL-9, TNF-b, TRAIL, IL-18, IL-21, TSLP." (PMID 37468934, 2023). "Intratumoral microbiota enhanced the secretion of specific chemokines (e.g., C-C motif chemokine ligand 2 (CCL2), CCL4, CXCL1 and CXCL10) and interleukins (e.g., IL-1β, IL-6 and IL-10) into the surrounding milieu, leading to T cell exclusion and tumor growth." (PMID 37868956, 2023). "Increasing evidence suggests that MDSCs also play an important role in the development of HCC, CCL2 and CCL5 from tumour cells and facilitate infiltration of MDSCs into the TME." (PMID 37542324, 2023). "TAMs derive from circulating monocytes and are directed into the tumor by chemokines such as CCL5, CCL2, and CCL17." (PMID 38008713, 2023). "The chemokine CCL2 can be expressed in the TME by stroma cells, endothelial cells, tumor cells or leukocytes, forming a CCL2 gradient within the tissue." (PMID 37849753, 2023). "These c-Rel+IL-1βhiArg1− rMos promote tumor growth by suppressing T cell function and maintaining a suppressive TME through IL-1β-CCL2 crosstalk." (PMID 37443711, 2023). "MCP-1 (Monocyte chemoattractant protein-1 or CCL2) plays a role in recruiting and attracting TAMs to tumour sites." (PMID 37397243, 2023). "However, whether CCL2 directly acts on tumor cells remains unclear." (PMID 37153567, 2023). "Biomolecules recruiting monocytes, such as VEGF, CSF-1, CCL2 and CCL5, are involved in macrophage recruitment to the tumor area and, as a result, in increasing the number of TAMs." (PMID 37999184, 2023). "They identified increased C-C motif chemokine 2 (CCL2) secretion, recruiting Iba1+ myeloid cells, further promoting proliferation of brain metastatic tumour cells." (PMID 37670020, 2023). "Some chemokines described in this review, including CCL2, CCL5 and CCL15, can also recruit effector cells (including NK cells, T lymphocytes) that are critical for tumor clearance." (PMID 36173487, 2023). "Depleting fibroblastic STAT3 or CCL2, or murine CCR2 attenuated the FAP-induced MDSC infiltration and tumor-promoting effects in vivo." (PMID 36708970, 2023). "At the same time, serum levels of proinflammatory cytokines such as CCL2, IL‐6, and MIP‐1β were also significantly elevated, indicating an enhancement of the systemic anti‐tumor immune response after P5091@RMPs‐R4F treatment." (PMID 36698296, 2023). "For instance, circulating hypoxia activated hypoxia-inducible factor 1(HIF-1) and NF-κB in tumor cells, which resulted in increased production of VEGF-A, CCL2/MCP-1, CXCL1, CXCL8/IL-8 and prostaglandin E2(PGE2)." (PMID 36173487, 2023). "Chemokines such as CCL2 and CXCL16 can have direct effects on tumor cells, promoting cell motility and invasion." (PMID 37301772, 2023). "In parallel, CCL2 immunostaining scoring in 10 TPAC mice showed that the nerves scored again highest when compared with acinus (P ˂ 0.0001), tumor (P ˂ 0.0001), immune cells (P ˂ 0.0001), and fibroblasts (P ˂ 0.0001)." (PMID 37607005, 2023). "Secondly, Mφ-SDNPs can scavenge CCL2 and CSF1 in the tumor site and exploit the SIRPα-CD47 interaction to remodel the tumor microenvironment." (PMID 38111068, 2023).
tumor (continued). "TAMs originate from mononuclear precursors, and the effect of chemokines, such as CSF-1, CCL2, VEGF, and TGF-β, is required for monocytes to reach the tumor site in the colon." (PMID 36709284, 2023). "The pathway linking PTEN loss to the promotion of brain metastasis involved nuclear factor-κB signaling and C-C motif chemokine 2 (CCL2)-induced myeloid cell recruitment, indicating reciprocal crosstalk between tumor cells and the brain microenvironment." (PMID 38707985, 2023). "Another phase 2 clinical trial (NCT01015560) investigating a mAb to human CCL2 (MLN1202, plozalizumab) in bone metastasis of unspecified tumours was conducted in a cohort of 44 subjects." (PMID 37170733, 2023). "As stated, CCL2, CXCL12, IL-15, CD20, and CD70 are immune-related genes that have a certain significance for tumor development and immunotherapy." (PMID 37494663, 2023). "Chemokine axes such as C-C motif chemokine ligand 2 (CCL-2)/C-C motif chemokine receptor 2 (CCR2) and CCL-5/CCR5 can recruit monocytes/macrophages from the blood to the tumor region." (PMID 36902024, 2023). "In particular, CCL2 and CCL3 have been found to have direct protumor effects by promoting tumor invasion and proliferation, survival, motility, and stemness and preventing apoptosis." (PMID 37373025, 2023). "The NOTCH1 pathway forms a positive feedback loop between the tumor cells and TAMs, and its overexpression increases the expression of NOTCH1 and JAGGED1 and upregulates the expression of IL-1β and CCL2, thereby leading to M2 polarization." (PMID 37894541, 2023). "Many studies have shown the positive regulatory role of CCL2 in tumor growth; indeed, we also observed reduced proliferation in TRAMP-C1 following CCL2 knockdown by siRNA." (PMID 36672395, 2023). "Tumor cells and stroma, which make up the hypoxic core of the tumor microenvironment, promote the production of VEGF, CCL2, CCL5, CSF-1, EMAP-II, endothelin-2, SEMA3A, oncostatin M, and eotaxin." (PMID 37056346, 2023). "A protumorigenic TME is saturated with several supporting tumor growth cytokines like interleukin (IL)-4, IL-6, and IL-10 as well as transforming growth factor (TGF)-β, interferon (IFN)-γ, and chemokines such as chemokine (C-C motif) ligand 2 (CCL2)." (PMID 38033495, 2023). "Therapeutic blocking of the CCL2/CCR2 axis counteracts the tumor-induced immunosuppression and leads to the activation of a CD8+ T cell anti-tumor response, attributed to the inhibition of MoMF infiltration and TAM polarization." (PMID 36845555, 2023). "Exposure of microglial cells to glioblastoma cell-derived EVs revealed an upregulation of the expression of the pro-tumor factors CXCL1/10, CCL2/CCL5 and IL-6 as well as an increase in their own proliferation." (PMID 37700840, 2023). "In liver cancer, CAFs crosstalk with immune cells through CCL2, CLCF1, or endosialin release, favoring tumoral infiltration of MDSCs, N2 neutrophils, or M2 macrophages with resultant tumor propagation." (PMID 36708970, 2023). "We evaluated expression levels of key factors CCL-2, RANKL and MMP-9 and found higher expression of RANKL and MMP-9 in tumor tissue compared to normal breast tissue." (PMID 36890825, 2023). "Prior reports have shown that IFN-β, CXCL10, and CCL2 are increased after ATRi plus RT in the TME and in tumor cells cultured in vitro, and this has been attributed to tumor cell–intrinsic signaling." (PMID 36810257, 2023). "In malignant melanoma, targeted inhibition of HIF-1α induced high levels of CCL2 and CCL5 expression and then increased the invasion of tumor-killing NK cells, CD3+, CD4+, and CD8+ T cells in tumor tissues." (PMID 36675491, 2023). "Considering the role of CCL2 in MDSC recruitment and fostering a tumor permissive environment, CCl2 blockade would potentiate immune response and augment immunotherapy." (PMID 38313431, 2023).
tumor (continued). "CCL2, also known as monocyte chemotactic protein-1 (MCP-1) or small inducible cytokine A2 (SCYA2), is a highly potent chemoattractant of monocytes/macrophages to areas of tissue injury and inflammation, as well as to tumor areas." (PMID 37190507, 2023). "The chemokine CCL2 and its receptor CCR2 have been shown to play multiple roles in tumorigenesis and tumor cell metastasis." (PMID 36374225, 2023). "In mouse models, CCL2 and CCL9 were shown to contribute to the mobilization of myeloid-derived suppressor cells, potentially facilitating tumor growth." (PMID 36982370, 2023). "Chemokine CCL2 can recruit monocytes with highly expressed CCR2, while targeted inhibition of CCR2 can decrease the recruitment of M2 macrophages and induce tumor infiltration of activated CD8+ T cells." (PMID 37494663, 2023). "CCL2 and CCL5 have been suggested to act as important mediators between tumor and host cells in the tumor microenvironment." (PMID 36766725, 2023). "The tumor-promoting effect of HDM was significantly decreased by heat treatment of the HDM extract and was inhibited by NLRP3, IL-1β, and CCL2 neutralization, or ICS treatment." (PMID 36670473, 2023). "Chemokines produced by tumor cells can drive the infiltration of immune cells into the TME and chemokine (C-C motif) ligand 2 (CCL2), also known as monocyte chemoattractant protein-1 (MCP-1) plays an important role in this context." (PMID 37849753, 2023). "Our study demonstrated that low expression of CDK5RAP3 promotes CCL2/CCR2 signalling to regulate the recruitment of monocytes and macrophages to tumour tissues." (PMID 35999359, 2023). "Under the influence of GBM, GAMs are a major source of inflammatory cytokines (e.g., IL-1β, IL-8, IL-10) and chemokines (e.g., CCL2, CCL4, CCL5) that support GBM growth and mitigate anti-tumor immune function." (PMID 37368789, 2023). "By causing monocytes to secrete the matrix metalloproteinase 9 (MMP9) enzyme, CCL2 and CCL3 can promote the extravasation of tumor cells." (PMID 37373025, 2023). "The results show a decrease in the level of CCL2 with 5-ADC and 5-ADC with PDT in correlation with tumour depletion." (PMID 38022682, 2023). "By secreting TGF-β, CCL2, CCL5, IL-6 etc., CAFs recruit immunosuppressive cells into the tumor stroma, which contributes to cancer metastasis and progression." (PMID 36843593, 2023). "Gene expression analysis showed that chemokines such as Ccl2 and Ccl8 and cell proliferation markers such as Mki67 and Birc5 were highly expressed in cluster 3, indicating that 8 mg/kg of smTRAIL may induce tumor cell “activation” and secretion of chemokines to recruit immune cells." (PMID 37605148, 2023). "Although both WT and CCL2 KO MSCs reduced tumor growth in mice injected with the parental TRAMP-C2, we suspected that the WT MSCs can be tumor-promoting in certain situations." (PMID 36672395, 2023). "Chemokines secreted by either tumor cells or cells reside in TME have impacts on PMN, including CXCL1, CCL2, CCL9 and CCL15." (PMID 37936694, 2023). "Pro-tumorigenic chemo/cytokines such as IL-6, IL-10, CCL2, and CCL5 were decreased in NLRC5+ tumor-bearing ascites, correlating with significantly decreased frequency of tolerogenic DC2s subsets in this compartment." (PMID 38235131, 2023). "The mRNA levels of CCR2, CCL2, VEGF, NF-κB, c-Myc, vimentin, and IL33 were determined in the CT26 cell line and then tumor tissues (after 21 days), by qRT-PCR." (PMID 37325423, 2023). "These monocytes and macrophages in luminal tumor hubs upregulate inflammation (MMP12 and MMP9), myeloid cell recruitment (CCL2 and CCL7), and tumor growth–promoting genes (VEGF and EREG)." (PMID 37492581, 2023). "Multiple chemokines (such as C-C motif chemokine 2(CCL2)) and cytokines (such as members of the vascular endothelial growth factor family) can recruit circulating inflammatory monocytes into tumor tissue." (PMID 37654704, 2023).